RRM1 (ribonucleotide reductase catalytic subunit M1)
Diseases named in the same sentence as RRM1 in open-access papers (continued):
Sharing a sentence is not in itself a finding about the gene and the disease.
amyotrophic lateral sclerosis (3 papers, 2014 to 2025). Amyotrophic lateral sclerosis (ALS) is a neurodegenerative disease characterized by progressive muscular paralysis reflecting degeneration of motor neurons in the primary motor cortex, corticospinal tracts, brainstem and spinal cord. "Moreover, RRM1 of the amyotrophic lateral sclerosis-linked mutant D169G binds DNA as efficiently as the wild type; nevertheless, it is more resistant to thermal denaturation, suggesting that the resistance to degradation is likely linked to TDP-43 proteinopathies." (PMID 24464995, 2014). "TDP‐43 has two RNA binding domains (RRM1 and RRM2) and a C‐terminal low complexity glycine‐rich domain (LCD), in which mutations causative for amyotrophic lateral sclerosis (ALS) are clustered." (PMID 29764981, 2018).
lymphoma (3 papers, 2013 to 2024). A malignant (clonal) proliferation of B- lymphocytes or T- lymphocytes which involves the lymph nodes, bone marrow and/or extranodal sites. "Two lymphomas in kidneys were found only in the Rrm1+/Y285A mice, suggesting that this is a unique cancer phenotype resulting from the Rrm1-Y285A mutation." (PMID 39360631, 2024). "Among the Rrm1+/Y285A mice that had lymphomas, three developed lymphomas in the lungs, two in the liver, one in the spleen and one in the intestine." (PMID 39360631, 2024). "While no abnormalities were observed in WT mice at this stage, four of the Rrm1+/Y285A mice had lymphomas in one or multiple organs." (PMID 39360631, 2024). "Both WT and Rrm1+/Y285A mice developed lymphomas in the spleen, liver, intestines and lungs." (PMID 39360631, 2024). "However, lymphomas developed in the Rrm1+/Y285A mice as early as at 68 weeks, but only began to appear at 105 weeks in the WT mice." (PMID 39360631, 2024). "The difference in the expression patterns of genes between the healthy and DLBCL samples in the canine dataset highlighted important lymphoma-specific up-regulated genes including DHFR, MS4A1, MYC, POLA1, POLE, RRM1, TOP2A and TYMS." (PMID 24023754, 2013).
prostate carcinoma (3 papers, 2019 to 2023). A carcinoma that arises from epithelial cells of the prostate gland. "For example, phosphorylation of RRM1 regulates DNA replication and ATR inhibition vulnerability, while RRM2 drives aggressive prostate cancer and hepatocellular carcinoma, suggesting their importance for targeted therapies 38,39." (PMID 37737478, 2023). "Our mechanistic studies suggest that Bcl‐xL, Bim, CHK1, c‐Myc, Mcl‐1, RRM1, RRM2 and Wee1 play a role in the antitumour activity of CUDC‐907 against prostate cancer." (PMID 32459381, 2020). "Our functional studies provide direct evidence that CUDC‐907 induces DNA damage and apoptosis in prostate cancer cells at least partially through down‐regulation of CHK1, Wee1, RRM1 and RRM2." (PMID 32459381, 2020). "Our real‐time RT‐PCR analyses revealed that CUDC‐907 treatment significantly decreased the transcript levels for CHK1, Wee1, RRM1 and RRM2 in prostate cancer cells, indicating a potential transcriptional mechanism responsible for the down‐regulation of these proteins by the agent." (PMID 32459381, 2020).
anemia (2 papers, 2023 to 2024). A reduction in the number of red blood cells, the amount of hemoglobin, and/or the volume of packed red blood cells. "In CLL patients, RRM1 mRNA expression was higher in patients without anemia, absence of lymphadenopathy, and 17p gene deletion." (PMID 38435839, 2024). "RRM1 mRNA levels were higher in patients without anemia (p = 0.026) or lymphadenopathy (p = 0.005)." (PMID 36811764, 2023).
colorectal cancer (2 papers, 2013 to 2021). A primary or metastatic malignant neoplasm that affects the colon or rectum. "ERCC1, RRM1, RRM2, and hENT-1 have been proposed as potential predictive biomarkers of treatment response in several types of tumors, including lung, pancreatic, ovarian, and colorectal cancer." (PMID 34353292, 2021).
Lymphadenopathy (2 papers, 2023 to 2024). Enlargement (swelling) of a lymph node. "Α “methylated” status (FΜ) of RRM1 gene promoter was correlated with the presence of lymphadenopathy (p = 0.016)." (PMID 36811764, 2023). "The methylated status of RRM1 promoter significantly correlated with lymphadenopathy presence." (PMID 38435839, 2024). "In our study, higher RRM2 mRNA levels were associated with the absence of lymphadenopathy and a Rai stage of 0, which also could suggest a favorable prognosis profile, and be supported by our hypothesis regarding RRM1." (PMID 36811764, 2023). "Moreover, the finding of a correlation between methylation status and the presence of lymphadenopathy is very interesting, as lymphadenopathy is an important feature of CLL, and has also been related both with RRM1 and with RRM2 mRNA expression in our study, which make RNR a possible biomarker." (PMID 36811764, 2023).
medulloblastoma (2 papers, 2017 to 2018). A malignant, invasive embryonal neoplasm arising from the cerebellum. "High expression of MRP1 (89%, 8/9 tumors), TUBB3 (86%, 18/21 tumors), PTEN (85%, 28/33 tumors), TOP2A (84%, 26/31 tumors), thymidylate synthase (TS; 80%, 24/30 tumors), RRM1 (71%, 15/21 tumors), and TOP1 (63%, 19/30 tumors) were found in medulloblastoma." (PMID 29869738, 2018).
Pleural effusion (2 papers, 2014 to 2021). The presence of an excessive amount of fluid in the pleural cavity. "We therefore studied pleural effusions with respect to the drug sensitivity of tumor cells and immunoreactivity of two proteins associated with drug resistance, ERCC1 and RRM1." (PMID 25253633, 2014). "The proportion of malignant cells and RRM1 reactivity in the pleural effusions correlate to drug sensitivity and survival time." (PMID 25253633, 2014).
rectal cancer (2 papers, 2015 to 2018). A primary or metastatic malignant neoplasm that affects the rectum. "Our group identified a 4-gene profile (C-MYC, GNG4, POLA, and RRM1) associated with response to preoperative chemoradiotherapy in rectal cancer patients." (PMID 26504848, 2015).
retinoblastoma (2 papers, 2024). A malignant tumor that originates in the nuclear layer of the retina. "This is strengthened by the observation that the mRNAs for E2F1 and E2F2, cyclins A1, A2 and cyclins E1 and E2 as well as the mRNAs for the ribonucleotide synthase subunits RRM1 and RRM2 are high in retinoblastoma primary tumors." (PMID 38332874, 2024). "For instance, studies have shown that the constitutively active retinoblastoma tumor suppressor can attenuate the expression of specific dNTP synthetic cellular enzymes, including DHFR, RRM1, RRM2, and thymidylate synthase (TS)." (PMID 39339888, 2024).
small cell lung carcinoma (2 papers, 2019 to 2021). Small cell lung cancer (SCLC) is a highly aggressive malignant neoplasm, accounting for 10-15% of lung cancer cases, characterized byrapid growth, and early metastasis. "Although ribonucleotide reductase (RNR) is known to catalyze the rate-limiting step of de novo deoxyribonucleotide triphosphate (dNTP) synthesis, the biological function of the RNR large subunit (RRM1) in small-cell lung carcinoma (SCLC) remains unclear." (PMID 34188151, 2021). "We found that the mRNA expression of RRM1, RRM2, and RRM2B genes were up-regulated in 57.9% (11 of 19), 78.9% (15 of 19), and 0% (0 of 9), respectively, of the Oncomine cancer studies covering the four subtypes of LUSC, LUAD, large cell lung carcinoma (LCLC), and small cell lung carcinoma (SCLC)." (PMID 31637211, 2019).
adenoma (1 paper, 2024). A neoplasm arising from the epithelium. "Apart from one case of pulmonary adenocarcinoma in the oldest WT mice, all of the adenomas were found only in the Rrm1+/Y285A mice with an onset at ∼95 weeks." (PMID 39360631, 2024).
African trypanosomiasis (1 paper, 2025). "Trypanosoma brucei, the causative agent of human African trypanosomiasis, encodes a ‘classical’ La protein (TbLa) composed of a La-motif, two RNA recognition motifs (RRM1 and RRM2α), a C-terminal short basic motif (SBM), and a nuclear localization signal (NLS)." (PMID 40637228, 2025).
ANE syndrome (1 paper, 2018). "Unlike RRM1, tested UHM substitutions in PD invariably reduced PUF60 expression, possibly through impaired folding, as shown for a RRM3 substitution in RBM28 in the ANE syndrome." (PMID 29788428, 2018).
astrocytomas (1 paper, 2016). "EGFR aberrations including gene amplification and EGFRvIII mutation, PTEN mutation, as well as TOP2A, RRM1 and TS overexpression were significantly more prevalent in GBM than grade III astrocytomas." (PMID 26933808, 2016).
benign pancreatic tumors (1 paper, 2021). "We also documented the absence of RRM1 expression in normal pancreatic tissues and benign pancreatic tumors." (PMID 34111175, 2021).
bladder tumour (1 paper, 2022). "To determine whether TOP2A and RRM1 expression plays a role in tumour drug sensitivity, we measured the mRNA and protein levels of TOP2A and RRM1 in the bladder tumour cell lines BIU-87, KK47 and human embryonic bladder tissue derived cells CCC-HB-2 by RT-qPCR and Western blot analysis." (PMID 35711974, 2022).
brain tumor (1 paper, 2023). "In sharp contrast, RRM1 T52A expression strongly enhanced the inhibitory effects of TMZ on brain tumors with corresponding extension of survival time." (PMID 37737247, 2023). "RRM1 T52A expression, genetic interruption of HPRT1-mediated AICAR production, or administration of 6-mercaptopurine (6-MP), a clinically approved inhibitor of HPRT1, blocks TMZ-induced AMPK activation and sensitizes brain tumor cells to TMZ treatment in mice." (PMID 37737247, 2023).
breast tumor (1 paper, 2013). "This study demonstrated the presence of RRM1 and RRM2B copy number changes in primary breast tumor specimens." (PMID 24215511, 2013). "In summary, this study revealed the occurrence of RRM1 and RRM2B aberrations in primary breast tumor specimens." (PMID 24215511, 2013).
CHARGE syndrome (1 paper, 2023). CHARGE syndrome is a multiple congenital anomaly syndrome characterized by the variable combination of multiple anomalies, mainly Coloboma; Choanal atresia/stenosis; Cranial nerve dysfunction; Characteristic ear anomalies (known as the major 4 C's). "In human disease with “ribosomopathy”, some germline variants of the FIR/PUF60 gene, generating truncated protein lacking RRM1, RRM2, P62-binding site, or RRM3/UHM, have been reported in Verheij and CHARGE syndromes." (PMID 38139171, 2023).
chordoma (1 paper, 2025). Chordomas are rare malignant tumors arising from embryonic remnants of the notochord in axial skeleton. "RRM1, the large catalytic subunit of ribonucleotide reductase responsible for generating deoxynucleoside triphosphates for DNA synthesis, is inhibited by gemcitabine, which is used to treat various cancers but whose efficacy in chordoma has not yet been tested." (PMID 40901948, 2025).
chronic myeloid leukaemia (1 paper, 2022). "Several RNR inhibitors are also used in anti-leukaemia therapies, such as hydroxyurea (HU) that targets RRM2 to treat chronic myeloid leukaemia (CML) and AML and the ribonucleoside analogues cytarabine and clofarabine that target RRM1 to treat acute leukaemia." (PMID 36230632, 2022).
ependymoma (1 paper, 2018). A WHO grade II, slow growing tumor of children and young adults, usually located intraventricularly. "This ependymoma cohort showed minimal alterations in gene amplifications and mutations but had high expression rates of DNA synthesis and repair enzymes such as RRM1 (47%), ERCC1 (48%), TOPO1 (62%) and class III β-tublin (TUBB3) (57%), which are also all associated with chemoresistance." (PMID 29487694, 2018). "Notably, ependymomas frequently overexpressed proteins implicated in DNA synthesis, transcription, and repair and/or drug resistance, including BCRP (5/7 [71%]), RRM1 (14/30 [47%]), ERCC1 (13/25 [48%]), TUBB3 (12/21 [57%]), TOPO1 (23/37 [62%]), and MRP1 (8/14 [43%])." (PMID 29487694, 2018). "We found that proteins involved in DNA synthesis (e.g. RRM1), transcription (TOPO1), and repair (ERCC1) are enriched in ependymoma." (PMID 29487694, 2018).
esophageal cancer (1 paper, 2014). A primary or metastatic malignant neoplasm involving the esophagus. "The expression levels of ERCC1, TYMS, TUBB3, RRM1 and TOP2A were determined using a microarray technique, while Spearman’s rank correlation analysis was used to determine the strength of the correlations between the expression levels of the biomarkers and the pathogenesis of esophageal cancer." (PMID 24926347, 2014).
esophageal squamous cell carcinoma (1 paper, 2014). Esophageal squamous cell carcinoma (ESCC) is a type of esophageal carcinoma (EC) that can affect any part of the esophagus, but is usually located in the upper or middle third. "However, to the best of our knowledge no study has been conducted using ERCC1, TYMS, TUBB3, RRM1 and TOP2A simultaneously in esophageal squamous cell carcinoma (ESCC)." (PMID 24926347, 2014).
gastric adenocarcinoma (1 paper, 2013). "RRM1 expression was significantly higher in cancerous tissue and heterogeneously expressed in the histological subtypes of gastric adenocarcinoma." (PMID 23922955, 2013).
head and neck cancer (1 paper, 2023). A primary or metastatic malignant neoplasm affecting the head and neck. "High expression of free circulating RNA of Ribonucleotide Reductase Catalytic Subunit M1 (RRM1) gene was significantly associated with increased risk of grade 3 Head and Neck cancer." (PMID 37091783, 2023).
hepatoblastoma (1 paper, 2014). Hepatoblastoma (HB) is a malignant hepatic tumor and is the most common pediatric liver cancer. "For example, one abstract stated the following: “Taq1 digestion of PCR products revealed that both alleles were transcribed in all samples where both were presented at the genomic level, indicating that the RRM1 locus is not subjected to imprinting in Wilms' tumour or hepatoblastoma”." (PMID 24915461, 2014).
metastatic tumors (1 paper, 2015). "In addition, RRM1 was more highly expressed in primary tumors than metastatic tumors (P = 0.041), while ERCC1 was more highly expressed in metastatic tumors than primary tumors (P = 0.066)." (PMID 26200905, 2015).
neurofibroma (1 paper, 2017). An intraneural or extraneural neoplasm arising from nerve tissues and neural sheaths. "PLK1,RRM1, and RRM2 mRNA levels were increased in MPNST compared to benign neurofibroma tissue, and the protein level of PLK1 was increased in the MPNST cell lines compared to normal Schwann cells, indicating an increased dependence on these drug targets in malignant cells." (PMID 28556483, 2017). "We did not observe any significant difference in RRM1 or its activator and binding partner RRM2 in the MPNST cell lines as compared to HSC1; however, these genes were both significantly upregulated in MPNST patient tumor samples as compared to benign neurofibromas." (PMID 28556483, 2017).
oral carcinoma (1 paper, 2008). "Increased RRM1 and RRM2 activity was identified in highly metastatic tumour cells, whereas overexpression of RRM2 in human oral carcinoma cells was shown to be associated with increased invasive potential, probably through NF-κB and MMP-9." (PMID 18414411, 2008).
pancreatic diseases (1 paper, 2021). "RRM1 expression was also examined in different types of low-grade malignant pancreatic diseases such as intraductal papillary mucinous neoplasia (IPMN) with low and intermediate-grade dysplasia, serous cyst neoplasia (SCN), and mucinous cyst neoplasia (MCN)." (PMID 34111175, 2021).
pancreatic ductal carcinoma (1 paper, 2012). "We investigated the mRNA and protein expression of ERCC1 and RRM1 by RT-PCR and immunohistochemistry (IHC) in formalin-fixed, paraffin-embedded pancreatic ductal carcinoma (PDA) tissues." (PMID 22436573, 2012).
renal adenoma (1 paper, 2024). An adenoma arising from the renal cortex. "Two renal adenomas were observed only the Rrm1+/Y285A mice, indicating tissue-specific susceptibility to altered dNTP pools." (PMID 39360631, 2024).
renal carcinoma (1 paper, 2024). A carcinoma arising from the epithelium of the renal parenchyma or the renal pelvis. "Moreover, full-length A1CF, but not an RRM1 deletion mutant, promoted cell proliferation in renal carcinoma cells." (PMID 38612387, 2024).
rhabdomyosarcoma (1 paper, 2017). A rare aggressive malignant mesenchymal neoplasm arising from skeletal muscle.
serous carcinomas (1 paper, 2014). "BCRP, ER, MGMT, and RRM1 proteins were overexpressed in 85%, 47%, 93%, and 47% of serous carcinomas, respectively." (PMID 27231557, 2014). "In this particular study, BCRP, ER, MGMT, and RRM1 proteins were overexpressed in 85%, 47%, 93%, and 47% of serous carcinomas, respectively." (PMID 27231557, 2014).
signet ring cell adenocarcinoma (1 paper, 2013). "RRM1 was highly expressed in the papillary (61.9%), tubular (59.6%) and undifferentiated adenocarcinomas (55.4%), but relatively lower in the mucinous (34.4%) and signet ring cell adenocarcinoma subtypes (14.3%)." (PMID 23922955, 2013).
Splenomegaly (1 paper, 2024). Abnormal increased size of the spleen. "Before reaching 100 weeks, seven of the Rrm1+/Y285A mice showed splenomegaly, whereas only two of the WT exhibited this condition." (PMID 39360631, 2024).
Stroke (1 paper, 2019). Sudden impairment of blood flow to a part of the brain due to occlusion or rupture of an artery to the brain. "However, literature retrieval results showed little evidences that other hub genes MPP4, RRM2, RRM2B, RRM1 and VCP contributed to the molecular mechanism of stroke prognosis." (PMID 31690277, 2019).
Thrombocytopenia (1 paper, 2012). A reduction in the number of circulating thrombocytes. "In terms of grade 3/4 adverse events, MMS19L was related with total grade 3/4 adverse events (P = 0.024) and grade 3/4 thrombocytopenia (P = 0.035), while RRM1 was related with total grade 3/4 adverse events (P = 0.047) and grade 3/4 vomiting (P = 0.046)." (PMID 23118991, 2012). "SNPs of MMS19L were related with total grade 3/4 adverse events (OR = 1.091, P = 0.024) and grade 3/4 thrombocytopenia (OR = 1.119, P = 0.035), while SNPs of RRM1 were related with total grade 3/4 adverse events (OR = 5.159, P = 0.047) and with grade 3/4 vomiting (OR = 2.319, P = 0.046)." (PMID 23118991, 2012).
urothelial carcinoma (1 paper, 2019). A malignant neoplasm derived from the transitional epithelium of the urinary tract (urinary bladder, ureter, urethra, or renal pelvis). "In addition, there are also several studies that evaluated the predictive and/or prognostic value of RRM1 expression level in patients with urothelial carcinoma (UC)." (PMID 31340801, 2019).
Verheij syndrome (1 paper, 2023). "The germline mutation of FIR in RRM1 + RRM2 of CHARGE or Verheij syndrome would provide insights into the role of FIR variants in inhibiting homodimerization and affecting rRNA and mRNA transcription." (PMID 38139171, 2023).